TRAV13-1 (T cell receptor alpha variable 13-1)
Description:
V region of the variable domain of T cell receptor (TR) alpha chain that participates in the antigen recognition. Alpha-beta T cell receptors are antigen specific receptors which are essential to the immune response and are present on the cell surface of T lymphocytes. Recognize peptide-major histocompatibility (MH) (pMH) complexes that are displayed by antigen presenting cells (APC), a prerequisite for efficient T cell adaptive immunity against pathogens. Binding of alpha-beta TR to pMH complex initiates TR-CD3 clustering on the cell surface and intracellular activation of LCK that phosphorylates the ITAM motifs of CD3G, CD3D, CD3E and CD247 enabling the recruitment of ZAP70. In turn ZAP70 phosphorylates LAT, which recruits numerous signaling molecules to form the LAT signalosome. The LAT signalosome propagates signal branching to three major signaling pathways, the calcium, the mitogen-activated protein kinase (MAPK) kinase and the nuclear factor NF-kappa-B (NF-kB) pathways, leading to the mobilization of transcription factors that are critical for gene expression and essential for T cell growth and differentiation. The T cell repertoire is generated in the thymus, by V-(D)-J rearrangement. This repertoire is then shaped by intrathymic selection events to generate a peripheral T cell pool of self-MH restricted, non-autoaggressive T cells. Post-thymic interaction of alpha-beta TR with the pMH complexes shapes TR structural and functional avidity.
Synonyms: TCRAV13S1; TCRAV8S1; TRAV131
Gene: T-cell receptor variable (V) gene on chromosome 14 (21,868,839 to 21,869,365, forward strand). Ensembl gene ENSG00000211788.
Subcellular location: Cell membrane
Gene Ontology:
Biological process: response to bacterium
Cellular component: plasma membrane
Homologues: Orthologues: macaque TRAV13-1 (92% identical), mouse Trav10 (68% identical), mouse Trav10d (68% identical), mouse Trav10n (68% identical), mouse Trav5-4 (65% identical), mouse Trav5d-4 (65% identical), mouse Trav5n-4 (65% identical), mouse Trav5-1 (62% identical), rat AABR07017874.1 (62% identical), rat AABR07017838.1 (61% identical). Paralogues in human: TRAV13-2 (63% identical), TRAV5 (57% identical), TRAV7 (41% identical), TRAV24 (40% identical), TRAV20 (39% identical), TRAV17 (38% identical), TRAV6 (38% identical), TRAV39 (38% identical), TRAV36DV7 (37% identical), TRAV21 (36% identical), TRAV10 (35% identical), TRAV38-2DV8 (34% identical), and 11 more.
Diseases named in the same sentence as TRAV13-1 in open-access papers:
TRAV13-1 is named in the same sentence as 2 diseases in open-access papers, as found by Europe PMC text mining. Sharing a sentence is not in itself a finding about the gene and the disease. The quoted sentences say what the papers report.
atherosclerosis (1 paper, 2023). A disease characterized by the build-up of fatty material and calcium deposition in the arterial wall resulting in partial or complete occlusion of the arterial lumen. "Similarly, the expression levels of CD28, TRAT1, TRAV13-1, and LEF1 were related to smoking and smoking-related atherosclerosis." (PMID 37762221, 2023).
COVID-19 (1 paper, 2024). A disease caused by infection with severe acute respiratory syndrome coronavirus 2. "The expression of genes such as TRDV2, TRVD1, TRAV38-1, TRBV3-1, TRAV13-1, and TRBV2 was among the 15 most decreased in all data of severe COVID-19." (PMID 38262689, 2024).